CD44 (CD44 molecule (IN blood group))
Diseases named in the same sentence as CD44 in open-access papers (continued):
Sharing a sentence is not in itself a finding about the gene and the disease.
tumor (continued). "The localization of the tumor-promoting immune cells might be supported with the interaction of SPP1 and CD44 in the tumorous ECM." (PMID 37945567, 2023). "Subcutaneous models further confirmed the role of CD44 in tumor growth." (PMID 37509716, 2023). "Exploiting the therapeutic beta emission of 177Lu, this novel NGR-HA complex could be introduced in the workup of CD13- and CD44-positive targeted tumor radiotherapy." (PMID 37760428, 2023). "To identify cHB-LC11 cells in tissue slides derived from PDX mice, we used the continuously prominent tumor progression marker CD44, as well as the progenitor cell marker CK19, in combination with proliferation marker Ki67 and the pan MHC-class I Marker HLA-ABC." (PMID 38201286, 2023). "In those studies, the ratio of CD44 expression in the tumor periphery to expression in the tumor core (P/C ratio) could be evaluated as a marker of GBM invasiveness." (PMID 37760811, 2023). "Higher CD44 expression was associated with clinically poor prognostic features: age ≥ 70 years (p = 0.0166); inoperable disease (p = 0.0008); stage IV at diagnosis (p = 0.0241); BRAF mutated (p = 0.0111), high-grade tumor (p = 0.0084)." (PMID 36831554, 2023). "Additionally, the cancer stemness properties of the isolated CD44+ cells were confirmed by the formation of tumor spheroids and colonies." (PMID 36902135, 2023). "In addition, information flow mediated by SPP1 and CD44, regulate signaling pathways of tumor progression." (PMID 37675100, 2023). "We next examined whether other CSC markers like CD133 and CD44 are co-expressed with TRA in DU-145 tumor sections via immunofluorescent staining." (PMID 37153742, 2023). "We also found that OPN upregulated by HIF-2α under 5% O2 (moderate hypoxia) enhances the proliferation of GSCs and that silencing the OPN gene with its siRNA inhibits the cell growth, but elevates the expression of CD44, leading to the promotion of tumor cell migration and invasion." (PMID 37835592, 2023). "One study found that CD44+ cells of OSCC cross-talk with macrophages to promote stemness activities while another study reported STAT3 mediated expression of PDL-1 expression in CD44+ CSC leading to suppression of T cell mediated tumor immune response in OSCC." (PMID 37954619, 2023). "CD44+ GSCs possess SR and tumor initiation capacity as well as a drug-resistant nature." (PMID 37373242, 2023). "Additionally, the glucose metabolism-related protein GLUT1 and the tumor cell stemness marker CD44 were also found to be highly expressed in GC tissue." (PMID 37980488, 2023). "For instance, CD44-HA interaction activates Rho GTPases, leading to the remodeling of the actin cytoskeleton and the formation of cell protrusions, such as invadopodia, that facilitate tumor cell invasion." (PMID 37366874, 2023). "The process of differentiation has affected the CD44+ stemness properties, their viability, and the levels of both oncogenic and tumor suppressor micro RNAs, implying that CSC differentiation might be used as a novel therapeutic modality." (PMID 36902135, 2023). "Due to the EPR effect and the specific recognition of hyaluronic acid with the CD44 protein on the surface of tumor cells, nanodrugs effectively accumulated at the tumor site, then large amounts of Ca2+, Cu2+, and H2O2 could be released simultaneously in TME." (PMID 37064867, 2023). "This may be a reason why CD44 expression in the tumor periphery is higher in HI-type GBM than in LI-type GBM, even if one’s evaluating by either CD44 expression in the periphery alone or CD44 expression by P/C ratio." (PMID 37760811, 2023). "CD44 engagement by its ligands induces a vast array of intracellular pathways spanning from cell growth, survival, differentiation, and motility to the activation and homing of T lymphocytes as well as tumor development and metastasis." (PMID 37958334, 2023).
tumor (continued). "Since the inhibition of CD44 is reported to induce apoptosis and inflammation in skeletal tissues 31, the interactions of atypical tumor-suppressing proteins with cell-surface proteins such as CD44 may trigger apoptosis." (PMID 37056934, 2023). "However, some studies suggest that the oxidation of CD44 and HA decreases their mutual binding affinity, probably attenuating tumor cell growth and necrosis." (PMID 37107200, 2023). "Additionally, we observed a marked decrease in Ki‐67 and CD44 staining intensities in xenograft tumor tissues originating from cancer cells with SQLE depletion, as opposed to control cells." (PMID 37490552, 2023). "In vivo experiments also demonstrated that CD44 overexpression accelerated tumor formation in mice." (PMID 37509716, 2023). "Targeting CD44 could offer new avenues for the development of innovative anti-cancer therapies aimed at disrupting tumor progression and metastasis." (PMID 37593751, 2023). "As a principal receptor of HA, CD44 has an important influence on cell adhesion, which may affect tumor cells’ migration and aggressiveness." (PMID 36776876, 2023). "Depicts the proportion of tumor cells positive for CD44-positive expression." (PMID 37461792, 2023). "As few as 100 CD44+ neoplastic cells are sufficient to initiate tumour in nude mice." (PMID 37108193, 2023). "The results showed that the tumor protocell was with a similar structure as that of the native tumor cell, with DNA located in the core and the membrane wrapped on the surface, and the distribution of CD44 in protocell was also consistent with that of native tumor cell." (PMID 37400932, 2023). "MIF-activated CD44 is expressed in cells with dynamic proliferation, such as tumor cells." (PMID 37240298, 2023). "Furthermore, we explored the TMN plot to compare VEGFA, CTNNB1, MMP7, and CD44 oncogenes in tumor and metastatic CRC samples from RNA sequencing data (RNAseq)." (PMID 36672201, 2023). "In breast cancer, the CD44+CD24−/lowLineage− population was first shown to be 10- to 50-fold enriched with the ability to form tumors in immunodeficient mice relative to unfractionated tumor cells." (PMID 37176118, 2023). "The HA backbone could increase DOXO accumulation in tumor cells by exploiting the CD44-mediated uptake." (PMID 36839696, 2023). "Furthermore, intense CD44 IHC staining was observed in four metastasis tissues, and a positive correlation was found between CD44 expression, ccRCC tumor stage, and unfavorable patient survival." (PMID 37509716, 2023). "As the primary ligand of CD44, hyaluronic acid (HA) as an integral part of the nanocomposite structure has been shown to be effective in promoting preferential drug accumulation at the tumor site and enhancing cellular uptake." (PMID 37287910, 2023). "Therefore, HA can target CD44 targeted signaling and is a promising candidate for polymer in delivering anti-cancer drugs to target specific tumor sites." (PMID 36826291, 2023). "This may be contributed to the importance of CD44 in tumor cell survival in the blood flow, decline of CD44 after chemotherapy and radiotherapy." (PMID 36895477, 2023). "CD44 is widely used in tumor biology and clinical oncology as a stem cell (SC) marker." (PMID 37005380, 2023). "A number of studies validated the potential of CD44 as a therapeutic target in various tumor types." (PMID 37398648, 2023). "Moreover, HA serves as a natural ligand for tumor-targeted drug delivery systems, as it contains the endocytic HA receptor, CD44, which is overexpressed in many cancer cells." (PMID 37242892, 2023). "The expression of CD44 may be related to the immune escape of tumor cells because it has a regulatory effect on immune checkpoint genes." (PMID 37316699, 2023). "Furthermore, micelles with HA-modified MZF resulted inMZF-HA for specific targeting of CD44 highly expressing tumor cells, such as A549 (human lung adenocarcinoma cell line)." (PMID 37376161, 2023).
tumor (continued). "A study on pancreatic and glioma cancer cells showed that methyl-β-Cyclodextrin depletes cholesterol in cell membranes and destroy lipid rafts, leading to an increase in CD44 extracellular lipid distribution, and promoting CD44 related tumor metastasis mediated by ADAM-10, a metalloproteinase." (PMID 37305043, 2023). "Mechanistically, CD44 activation has been associated with the activation of various oncogenic signalling pathways, including the PI3K/AKT and MAPK/ERK pathways, which regulate cell proliferation, survival, and tumor growth." (PMID 37958796, 2023). "Interaction of CD44 and cMET facilitated tumor cell migration, invasion, and metastasis." (PMID 36622753, 2023). "Researchers have already reported that CD44 is highly expressed in tumor initiating cells of ESCC." (PMID 37817249, 2023). "Additionally, the positive rate of CD44 staining in tumor sections was higher than that in para-tumor areas." (PMID 37553567, 2023). "Once infiltrated into the tumor tissues, however, neutrophils appear to lose the expression of both CXCR2 and CD44, an event that might help neutrophils to stay in tumor tissues." (PMID 36921037, 2023). "Hyaluronic acid-modified sEVs could target delivering doxorubicin (DOX) to tumor cells with high expression of CD44, thus triggering significant tumor cell death." (PMID 37242660, 2023). "That is, MAPK activation correlates with proliferation and transcription factor CREB activation in the region of the tumor proliferation area, whereas PI3K activation correlates with CD44 expression, which strongly promotes tumor invasion in the region of the tumor border zone in GBM." (PMID 37835592, 2023). "Moreover, there was a significant increase in the Th17 (RORγt+ in CD4 + ) and activated and proliferating Th17 cells (RORγt+Ki67+CD44+ in CD4+) within the tumour in the Vacc DC-treated mice as compared to all the other groups." (PMID 37660049, 2023). "Finally, noradrenergic/CD44− and mesenchymal/CD44+ cells isolated from IC-pPDXC-63 and SK-N-SH were xenografted to nude mouse models and all formed tumours in vivo." (PMID 37887559, 2023). "Moreover, the surface-coating HA can serve as a targeted ligand for specifically binding with the overexpressed CD44 in the tumors for achieving tumor-targeting delivery." (PMID 37161591, 2023). "CD44 promotes both the invasion and proliferation of tumor cells via various signaling pathways." (PMID 37835592, 2023). "In addition, β4+ tumor cells metastasizing to the liver had signs of stemness (EpCam+CD44+CD24-ALDH1-β4+)." (PMID 36769251, 2023). "Describes the intensity of staining of tumor cells for CD44 expression." (PMID 37461792, 2023). "Additionally, HA was used to coat the CeO2 surface and target CD44-overexpressing tumor cells, while natZr was chelated on the Fe3O4-CeO2 surface to enable labeling with the radioisotope 89Zr." (PMID 37376161, 2023). "Consequently, a better understanding of the role of phenotype in tumor cells showing different activities of CD44 is required to create therapeutic strategies that target CD44 in GBM." (PMID 37835592, 2023). "The hyaluronan receptor CD44 plays a vital role in tumor cell growth and chemotherapy resistance." (PMID 36831425, 2023). "Furthermore, an in-depth analysis of phenotypic characteristics of β4+ tumor cells revealed a significantly increased proportion of E-cadherin+ and CD44+CD24- cells in patients with liver metastases compared to patients with lung or no distant metastases." (PMID 36769251, 2023). "In addition, activated PLTs overexpress the cell-adhesion molecule P-selectin, which can combine with P-selectin glycoprotein ligand-1 (PSGL-1) or CD44 on tumor cells, leading to PLT-tumor interplay." (PMID 36593970, 2023). "CD44 is a non-kinase transmembrane glycoprotein and associated with tumor progression, metastasis and drug resistance in NSCLC." (PMID 36895477, 2023). "Tumor-derived cells were CD44+ and CD10+ similar to transformed cells." (PMID 37709737, 2023).
tumor (continued). "Anti-CD44 agents can also stimulate T cells and monocytes to trigger the secretion of cytokines, promoting the immune system for antitumor activity and inhibiting tumor development and metastasis." (PMID 36759786, 2023). "Indeed, this specific interaction has been widely explored as a strategy to produce biomaterials able to detect CD44 overexpressed tumor cells." (PMID 37754116, 2023). "It is known that some tumor cells overexpress receptors for hyaluronic acid (HA) (CD44)." (PMID 37514119, 2023). "Interactions of HA with its binding proteins CD44 are important in promoting tumor progression." (PMID 37328876, 2023). "To verify this hypothesis, we blocked CD44 on tumor cells by using CD44 antibody and then incubated Plt‐M@P." (PMID 36925700, 2023). "Reduced CD44 expression leads to the growth suppression of tumor cells." (PMID 37189717, 2023). "Our review will focus on how tumor cells implement CD44 isoform switching." (PMID 38106992, 2023). "Furthermore, IHC staining revealed that the increased expression of Ki67 and CD44 (invasive marker) and the elevated infiltration of F4/80+ macrophages in cSERPINE2 overexpressing tumor tissues were blocked by anti-IL-6 antibody." (PMID 36797769, 2023). "A representative sample of the tumor was chosen and transferred into a new block of paraffin, the recipient block, to perform immunohistochemical analysis with the primary antibodies anti-CD44, PD-L1, and ATG7." (PMID 37173926, 2023). "We found that the osteopontin (OPN, encoded by SPP1)-CD44 pair was significantly enriched between macrophages and fibroblasts in different tumor types but was absent in most normal tissues." (PMID 36744260, 2023). "Previous studies showed that tumor cell-derived hyaluronan and soluble CD44 could induce the expression of IL-1β in monocyte and macrophages in primary tumor, respectively." (PMID 37443052, 2023). "In these cases, CD44 expression was higher in the invasive areas of the tumor." (PMID 36732018, 2023). "CD44-intracellular cytoplasmic domain (ICD) plays crucial roles in the intracellular signaling pathways for executing special cellular events, such as tumor progression, the maintenance of the stemness of cancer stem cells, aerobic glycolysis, and the production of CD44." (PMID 37835592, 2023). "In summary, these data suggest that cancer cells express elevated levels of the HA receptor, Cd44, which may be essential for sensing the matrix-rich environment, tumor cell motility/invasion, survival, and downstream signaling events." (PMID 36723776, 2023). "They surface-modified the liposomes by linking CO to achieve targeted uptake by CD44+ tumor cells." (PMID 38139233, 2023). "Here, engineered living material is constructed by living cells (human adipose–derived stem cells, hADSCs) and biomaterials (doxorubicin‐loaded Anti‐CD44 antibody‐modified hydroxyapatite) with dual functions of targeted residual tumor elimination and bone regeneration after surgery." (PMID 37156753, 2023). "Furthermore, compared with those of the LC or KC mouse group, the tumor tissues of the KLC mouse group exhibited elevated HCC markers (Cd44, Afp, Gpc3 and Ly6d) (P < 0.001 or P < 0.01)." (PMID 38124228, 2023). "Therefore, the establishment of CD44v-specific mAbs is essential for CD44-targeted tumor diagnosis and therapy." (PMID 37489367, 2023). "Tumor suppressor miRNA, miR34a, is believed to be frequently depleted in cancer tissues and it is associated with the genetic expression of multiple signaling pathways, including NOTCH-1, CD44, Bcl-2, Myc, Met, CDK-4/6, and various other biological molecules." (PMID 37149609, 2023). "It has been shown to express high levels of certain surface markers, such as CD44 and CD133, which are associated with cancer stem cells and may contribute to tumour initiation and resistance to chemotherapy." (PMID 38104117, 2023).
tumor (continued). "Dual loss of Rhamm and Cd44 does not modify primary tumor initiation or growth, and these mice also exhibit elevated metastases similar to the single knockout of Cd44 or Rhamm." (PMID 37349798, 2023). "One mechanism by which MMP-2 and MMP-9 activity induce cancer angiogenesis involves the cleavage of latent TGF-β in a CD44-dependent manner that may promote tumor growth and invasion." (PMID 36674806, 2023). "Hence, these EMT markers (E-cadherin and beta-catenin) and cancer stem cell marker (CD44) can be used as prognostic markers for predicting tumour growth and lymph node metastasis." (PMID 37012965, 2023). "Similarly, in in-vivo studies HA/Pt accumulated more in CD44-overexpressing tumors than AA/Pt, and proved to have superior efficacy in inhibiting tumor growth through PTT." (PMID 37376161, 2023). "CD44 is well known to promote tumor migration and invasion in GBM." (PMID 37835592, 2023). "OPN promotes tumor progression through binding to CD44 and integrin cell receptors." (PMID 38067149, 2023). "Therefore, elucidating the function of each CD44 isoform in a tumor is essential for the establishment of CD44-targeting tumor therapy." (PMID 37176118, 2023). "Treatment of mice with anti-CD44 antibodies significantly reduced tumor growth of shOPN AB1 cells." (PMID 37398648, 2023). "CD44 may thus play a crucial role in the regulation of invasion and proliferation as essential behaviors of tumor cells developing into GBM recurrence." (PMID 37835592, 2023). "CD44 levels can define stroma characteristics and the spectrum of tumour-infiltrating immune cells." (PMID 37108193, 2023). "However, in this study, the colony formation capacity of the HS578T-Hyg cells was comparable to M13HS-2 and -8 tumor hybrids, despite a M state and a lower fraction of CD44+CD104low cells." (PMID 38139138, 2023). "The experiment confirmed that the alkylamine modified HA could improve the targeting of HA to CD44, and the uptake efficiency of tumor cells was significantly improved." (PMID 37600308, 2023). "Immunohistochemical analysis showed that TIMP1/MMP9/CD44 ternary complex expression in primary tumor avatars paralleled an increase of the expression levels of TWIST, SNAIL in the xenograft metastasis, resembling the phenotypic landscape of PTC and ATC patient-derived primary and metastatic lesions." (PMID 36906579, 2023). "We also tested the expression of SOX2, Nanog, and CD44 in three tumor model groups." (PMID 38008751, 2023). "The transmembrane and cytoplasmic domains of CD44 have interactive properties with the cytoskeleton, as well as roles in signal transduction, which can up-regulate invasive tumor phenotypes and metastasis, leading to matrix degradation and cancer and tumor cell migration." (PMID 37762403, 2023). "Moreover, we observed SC144@HABN treatment lost its anti-tumor efficacy in mice bearing CD44-KO MC38 tumor cells pre-treated in vitro with CRISPR/Cas9 to knock-down the CD44 expression." (PMID 37553327, 2023). "Mice were treated with anti-CD44 mAb (10 mg/kg) at day 7, 12, 16, 19 post tumor implantation." (PMID 37398648, 2023). "Due to its role in the maintenance of stemness and the function of CSCs in tumor progression, CD44 could be an important prognostic marker." (PMID 36831554, 2023). "Meanwhile, in vivo limiting dilution assay (LDA) performed by xenograft experiment using a series of cell amounts as indicated revealed that YY2 overexpression decreased liver CSC frequency by > 10‐fold, as well as the expression of CSC markers CD44 and EpCAM in the xenografted tumor lesions." (PMID 37300334, 2023). "Strong green fluorescence could be detected in all the tumor sections, suggesting the expression of CD44 on the HepG2 cells." (PMID 36839952, 2023). "CD44 is thought to be a common receptor for NDDSs targeting tumor cells and TAMs at the same time." (PMID 36794651, 2023). "On the other hand, tumor cell segments displayed lower levels of CD44, CD40, and CD27." (PMID 38044986, 2023).